APOC3 (apolipoprotein C3)
Diseases named in the same sentence as APOC3 in open-access papers (continued):
Sharing a sentence is not in itself a finding about the gene and the disease.
diabetes (continued). "APOC3 3u386 GC/GG subjects with diabetes exhibited significantly higher triglyceride (P = 0.004), total cholesterol (P = 0.003) and glucose (P = 0.016) compared to CC subjects." (PMID 19424489, 2009). "APOC3 also plays a role in diabetes, in which elevated plasma concentrations of both the apolipoprotein and triglycerides increase vascular disease risk." (PMID 19424489, 2009). "This analysis showed that baseline plasma APOC3 levels associate with CVD risk more strongly in individuals with type 2 diabetes than in those with impaired fasting glucose or without diabetes." (PMID 40709279, 2025). "Diabetes altered 179 pathways in SMCs; of these, a full 161 were prevented by APOC3 ASO." (PMID 40709279, 2025). "Single-cell RNA-sequencing revealed that APOC3 silencing prevents a majority of diabetes-induced pathways in macrophages, endothelial cells, and smooth muscle cells, with inflammation as a major predicted upstream regulator, adding promise to APOC3 as a CVD target in diabetes." (PMID 40709279, 2025). "Diabetes altered 7 pathways in ECs, 3 of which were prevented by APOC3 silencing." (PMID 40709279, 2025). "Moreover, in the setting of diabetes, APOC3 silencing appears to have beneficial effects beyond those of ANGPTL3 silencing, preventing arterial free cholesterol accumulation." (PMID 40709279, 2025). "The top enriched pathway in diabetic mice strongly prevented by APOC3 silencing was neutrophil degranulation, but a pathway related to lipoprotein metabolism, driven by lipid-related genes including Abca1, Abcg1, Apoe, and Soat1 was also enriched by diabetes and prevented by APOC3 silencing." (PMID 40709279, 2025). "Together, the results indicate that diabetes enhances lipid signatures in intimal resident macrophages mediated by hepatic APOC3, but that several other diabetes-enriched pathways related to inflammation and metabolism are also prevented by APOC3 silencing." (PMID 40709279, 2025). "Thus, correcting the impaired TRL/RLP clearance by silencing APOC3 prevents a majority of diabetes-induced signatures in arterial cells and free cholesterol accumulation even when glucose levels are high." (PMID 40709279, 2025). "Likewise, in the fibroblast cluster diabetes altered 247 pathways, 235 of which were prevented by APOC3 ASO (Supplemental Excel 3)." (PMID 40709279, 2025). "In diabetes research, APOC3 has been shown to influence LDL binding." (PMID 39684468, 2024). "Multiple studies have confirmed that APOC3 plays an important role in diabetes-related CVD." (PMID 39684468, 2024). "Therefore, this review examines the complex metabolic cycle of APOC3, emphasizing the impact of APOC3-containing lipoproteins on human metabolism, particularly in patients with diabetes." (PMID 39684468, 2024). "Apolipoprotein C3 (APOC3) plays a critical role in regulating triglyceride levels and serves as a key predictor of cardiovascular disease (CVD) risk, particularly in patients with diabetes." (PMID 39684468, 2024). "APOC3 deficiency, however, did not protect against diabetes-induced injury, again in the absence of elevated TRLs." (PMID 38743496, 2024). "However, more research is needed on the impact of reducing APOC3 in relation to diabetes-related CVD." (PMID 39684468, 2024). "In addition to pharmacological interventions, lifestyle modifications, such as diet and exercise, have been shown to influence APOC3 expression and TRL levels, providing a comprehensive approach to managing cardiovascular risk in diabetes." (PMID 39684468, 2024). "Notably, of the three isoforms of APOC3, only apoCIII2 within LDL has been implicated in triggering inflammatory responses in patients with diabetes, including the production of interleukin (IL)-6, TNF-α, and IL-8." (PMID 39684468, 2024). "Including participants with diabetes would be important also because there are inconclusive indications that APOC3 inhibition could improve insulin sensitivity." (PMID 37972731, 2024).
diabetes (continued). "A gene-centric association analysis was performed on all directly genotyped and high-quality imputed SNPs within the APOC3 region with MAF ≥5% to identify gene variants associated with TG concentrations using multiple linear regression controlling for age, gender, BMI, diabetes, and PCs." (PMID 34548093, 2021). "Furthermore, based on the research available to date, new therapies that target apolipoproteins, such as APOC3, would be predicted to be effective in preventing CVD in patients with diabetes and elevated levels of APOC3." (PMID 32118048, 2020). "Furthermore, intensive insulin therapy but not blood glucose lowering by a sodium-glucose cotransporter 2 inhibitor was shown to prevent the effects of diabetes on APOC3 elevation." (PMID 32849290, 2020). "The selected features of the proposed classifier on the Set 1 were CETP TaqIB [rs708272], CETP A373P [rs5880], LPL D9N [rs1801177], ApoE, ABCAI R1587K [rs2230808], APOA5 C-1131T [rs662799], LPL HindIII [rs320], APOC3 SstI [rs5128], family history of obesity, and diabetes, and APOA1 MspI [rs2893157]." (PMID 30026888, 2018). "Associations between apolipoprotein C3 (APOC3) gene polymorphisms and impaired lipid and glucose metabolism are well-established, but potential connections between APOC3 polymorphisms, cognitive decline and diabetes deserve further attention." (PMID 19424489, 2009). "In contrast, for APOC3 3u386, cognitive function did not vary by genotype, but minor allele carriers (GC and GG) with diabetes exhibited higher plasma triglycerides." (PMID 19424489, 2009). "In a study that used multivariate regression analysis to evaluate patients without diabetes having systemic lupus erythematosus with blood glucose levels <110 mg/dL, a significant association was found between APOC3 and C-peptide (β coefficient, 0.27; 95% CI, 0.03–0.51 ng/mL; p = 0.030)." (PMID 39684468, 2024). "In addition, APOC3 appears to hold an important role as a CVD risk factor and mediator in people with diabetes, at least in the case of type 1 diabetes, in which plasma triglyceride levels are often within the optimal (<100 mg/dl) to borderline (100–150 mg/dl) range." (PMID 37972731, 2024). "Therefore, understanding how APOC3 affects the metabolism of TRLs and contributes to diabetes-related CVD is essential for developing potential therapeutic strategies, including monoclonal antibodies and small interfering RNA (siRNA) therapies aimed at reducing the APOC3 levels." (PMID 39684468, 2024). "The finding that APOC3 immunoreactivity colocalizes (indicated by orange/yellow areas) with APOB supports the hypothesis the APOC3-containing lipoprotein particles accumulating in lesions in the setting of diabetes may be remnant lipoprotein particles." (PMID 33554869, 2021). "For APOC3 3u386, associations were also evaluated separately in subjects with and without diabetes." (PMID 19424489, 2009). "Instead, based on the large number of highly significant cognitive and metabolic differences between subjects with and without diabetes, we evaluated genotypic associations with phenotypic traits separately (diabetics and non-diabetics) for APOC3 m482 and APOC3 3u386." (PMID 19424489, 2009). "Several studies have suggested that apolipoprotein C3 (APOC3) plays a significant role in the development of CVD in patients with diabetes." (PMID 39684468, 2024). "One predicted upstream regulator—D-glucose—was notably enhanced with diabetes but not prevented by APOC3 ASO in ECs, consistent with the lack of effect of APOC3 silencing on blood glucose levels." (PMID 40709279, 2025). "Here we demonstrate that plasma APOC3 predicts CVD events in individuals with diabetes more strongly than in those without diabetes." (PMID 40709279, 2025).
diabetes (continued). "Silencing mouse APOC3 by a liver-targeted antisense oligonucleotide lowers both cholesterol and triglycerides carried by TRL/remnants and LDL and prevents aortic free cholesterol accumulation in diabetes, while ANGPTL3 silencing reduces triglycerides." (PMID 40709279, 2025). "Similar to the EC data, a glucose metabolite, UDP-D-glucose, was identified as a predicted upstream regulator activated in both diabetes models and not prevented by APOC3 silencing." (PMID 40709279, 2025). "A dissociation of APOC3 levels from plasma triglyceride levels in some cases is also supported by mouse studies in which diabetes resulted in increased plasma APOC3, as compared with non-diabetic controls, when matched for plasma triglycerides." (PMID 37972731, 2024). "A cardiovascular outcome study on APOC3 lowering considering these criteria would provide a major advance in our understanding of APOC3 as a mediator of CVD risk in participants with and without diabetes." (PMID 37972731, 2024). "Previously, we reported that inverse associations of high-density lipoprotein (HDL) with cardiovascular disease and diabetes were only observed for HDL that lacked the pro-inflammatory protein apolipoprotein C3 (apoC3)." (PMID 33142714, 2020). "Although diabetes does not result in dramatic albuminuria in this model, silencing APOC3 prevented the increase in urinary albumin excretion associated with diabetes, suggesting that the improvement observed with APOC3 ASO is not due to an improvement in glycemia." (PMID 38743496, 2024). "Additionally, APOC3 may participate in the inflammatory response in both T1DM and T2DM, positioning APOC3 as a potential target in diabetes management." (PMID 39684468, 2024). "For subjects with diabetes in the current study, all three overall cognitive function scores (executive, memory and attention/concentration) were significantly lower compared to those without diabetes, independently of APOC3 genotype." (PMID 19424489, 2009). "Second, plasma levels of APOC3 predict CVD events in individuals with and without diabetes." (PMID 37972731, 2024).
Obesity (52 papers, 2010 to 2025). Accumulation of substantial excess body fat. "This study investigated the association between serum E2 and ApoC3 levels among individuals with obesity from China." (PMID 36855114, 2023). "In summary, ApoC3 was negatively and linearly associated with serum E2 levels in men and premenopausal women with obesity." (PMID 36855114, 2023). "Specifically, we found off-target C-to-T editing in obesity mice generated premature stop codons and non-synonymous mutations on obesity and metabolic disorder-associated genes, e.g., Igfbp2, C3, Apoe, and Apoc3." (PMID 36997536, 2023). "Finally, a number of conditions such as age, obesity, gender, hormonal status may influence the relationship between APOC3 gene polymorphisms and CHD." (PMID 22054125, 2011). "Significant placebo-adjusted decreases from baseline in blood pressure, low-density lipoprotein (LDL) cholesterol, triglycerides, ApoB, ApoC3, and hsCRP were observed following orforglipron treatment in participants with T2D and/or overweight or obesity." (PMID 40481478, 2025). "Protein-based subspecies of HDL, especially those containing apolipoprotein E (apoE) or apolipoprotein C3 (apoC3), offer a glimpse of a vast metabolic system related to atherogenicity, obesity, type 2 diabetes, and other diseases." (PMID 38438344, 2024). "Conversely, a 2-wk intervention with an isocaloric low-carbohydrate diet (<30 g/d) with high fat and protein contents reduced plasma APOC3 concentrations in patients with obesity who presented with NAFLD." (PMID 37304843, 2023). "Consistent with this, our study showed that the HTG group had higher ApoC3 levels than the control group, among individuals with obesity." (PMID 36855114, 2023). "DEGs included a wide range of obesity marker genes, including obesity and lipid metabolism genes, such as acyl-CoA thioesterase, carboxyl ester lipase, and apolipoprotein C3." (PMID 32899471, 2020). "Sik3, Apoa1, and Apoc3 have been shown to be associated with variations in total, HDL, LDL-cholesterol or triglyceride levels, and Cadm1 with obesity-related traits." (PMID 26555648, 2015). "Apolipoprotein A5 (APOA5) gene, located on chromosome 11 adjacent to APOA1/APOC3/APOA4 gene cluster with known functions in the metabolism of plasma lipids, also modulates the risk of obesity in a number of studies." (PMID 24903888, 2014). "Similarly, in this study we performed genetic association analyses in a cohort of Italian obese subjects, to test whether obesity would expose the association between the APOC3 rs2854116 and rs2854117 variants and ALT levels as surrogate markers of hepatic steatosis." (PMID 21663607, 2011). "APOM, APOA2, APOC3, and APOA1, all apolipoproteins, were associated with lipid transport and involved in the PPAR signaling pathway and cholesterol metabolism, which played important roles in obesity development." (PMID 40438591, 2025). "Given that APOA1, APOC3, and APOA4 are genes associated with obesity and are grouped together in the same cluster as APOA5, it is possible that mutations in one gene within the cluster may be caused by genetic variations in another gene." (PMID 38867151, 2024). "We found that ApoC3 deficiency did not accelerate obesity in DKO hamsters when compared to controls." (PMID 35187136, 2022). "APOA4 and APOC3 apolipoproteins were increased in the plasma of obese rats and four apolipoproteins were elevated in the heart (A1, APOA4, APOC3, and E), suggesting the high vulnerability of cardiac tissue toward the lipidomic changes accompanying diet-induced obesity." (PMID 33716957, 2021). "Moreover, other DEGs involved in the protection of obesity, such as apolipoprotein C3 (O/C 7.66), phospholipase C beta 1 (O/C −8.55), and phospholipase A2, group IIF (O/C 3) were differentially expressed." (PMID 32899471, 2020).
Obesity (continued). "Moreover, ApoC3 is extensively studied for potential use as a biomarker of disease, because changes in the ratio of its different glyco-isoforms occur in obesity, kidney disease, liver disease, and sepsis." (PMID 28210565, 2017). "One speculated mechanism is that the effect of APOA5 gene variants on the risk of obesity might be attributed to this locus being in interaction with other obesity-risk genes, such as APOA1, APOC3 and APOA4 genes." (PMID 24903888, 2014). "Thus, a reduction in 6-h circulating NEFA levels found in the current study may suggest less fat oxidation in subjects carrying the double risk alleles of the SNPs in APOC3 and APOE, which may increase risks of obesity as well as type 2 diabetes in these individuals." (PMID 36050800, 2022). "APOC3 and APOA4 are two potential protein candidates of obesity cardiomyopathy signatures which levels were elevated in cardiac muscle and plasma but rescued after weight loss." (PMID 33716957, 2021). "Serum APOC3 concentration has been shown to be positively associated with triglyceride levels, and smoking has been reported to lower the concentration of APOC3 but only in women without central obesity, indicating a sex-specific response which is influenced by obesity traits." (PMID 36776603, 2023).
type 2 diabetes (49 papers, 2008 to 2025). "The V162 minor allele is associated with an increase in triglycerides, total cholesterol, LDL, ApoB, ApoC3, the risk of type 2 diabetes, and a decrease in HDL." (PMID 40806580, 2025). "Here, we demonstrate that plasma APOC3 can predict renal functional loss in people with type 2 diabetes." (PMID 38743496, 2024). "The plasma APOC3 levels were also associated with higher TG levels and higher coronary artery calcification in patients with type 2 diabetes." (PMID 37448184, 2023). "APOC3 promotor variants increase type 2 diabetes risk and the need for insulin treatment, particularly among lean patients." (PMID 37834292, 2023). "A population-based prospective cohort (n =7,983) APOC3 -482T allele had increased type 2 diabetes risk." (PMID 25380998, 2014). "In contrast, apoC3 abrogates the benefit of apoE on reverse cholesterol transport, which may account for the association of HDL that contains apoC3 with type 2 diabetes and other diseases." (PMID 38438344, 2024). "Whether plasma APOC3 also predicts CVD risk in type 2 diabetes is less clear, as different studies show discrepant results." (PMID 37972731, 2024). "Indeed, the secretion rate of APOC3 is associated with elevated TRLs in subjects with type 2 diabetes." (PMID 37972731, 2024). "In addition to its role in triglyceride metabolism, APOC3 has been implicated in type 2 diabetes mellitus (T2DM) pathophysiology through mechanisms such as promoting pancreatic β-cell apoptosis, dysregulation of glucose metabolism, and influencing insulin resistance." (PMID 40282372, 2025). "Since underlying kidney disease is a strong risk factor for cardiovascular disease and kidney disease augments plasma levels of APOC3, we asked whether silencing APOC3 would have the same protective effect in a model of type 2 diabetes that also has underlying kidney disease." (PMID 38743496, 2024). "Patients with type 2 diabetes mellitus(T2DM) increased levels of circulating APOC3, and it has been linked to enhanced β-cell apoptosis." (PMID 22054125, 2011). "In another study in which plasma triglyceride levels were 150 mg/dl or lower, serum APOC3 levels positively predicted CVD in subjects with type 2 diabetes." (PMID 37972731, 2024). "APOC3 predicts kidney disease in people with type 2 diabetes, and APOC3 depletion prevents diabetic kidney disease by reducing the effect of triglyceride-rich lipoprotein on glomerular cells." (PMID 38743496, 2024). "Based on other studies, this suggests that apoC3 would likely be increased and, together with increases in TG and VLDL-C, would be expected to increase risk of type 2 diabetes and heart disease." (PMID 33807135, 2021). "Apolipoprotein C3 (ApoC3) secretion is elevated in patients with type II diabetes and its overexpression results in decreased adipose lipolysis and increased fatty acid uptake by adipose depots." (PMID 32883606, 2020). "To this end, we tested the role of APOC3 in DKD in type 2 diabetes." (PMID 38743496, 2024). "Plasma APOC3 predicts DKD progression in humans with type 2 diabetes." (PMID 38743496, 2024). "APOC3 levels might therefore increase in the pre-diabetic stage, before the development of overt type 2 diabetes." (PMID 37972731, 2024). "In addition to the reductions in TRLs, silencing APOC3 reduced blood glucose in a type 2 diabetes model, which has also been reported in humans." (PMID 38743496, 2024). "Treatment with liraglutide for 16 weeks in patients with type 2 diabetes showed the significant reduction of the secretion rate and plasma concentration of APOC3 after a fat‐rich meal shown by the injection of [5,5,5‐2H3]leucine and ultrasensitive mass spectrometry techniques." (PMID 37448184, 2023). "Associations of apoA1 in HDL that contained or lacked apoC3 each with liver fat content were not modified by age, sex, race, or type 2 diabetes status (all Pinteraction > 0.05)." (PMID 33142714, 2020).